ANP32AP1 (acidic nuclear phosphoprotein 32 family member A pseudogene 1)
Gene: Transcribed processed pseudogene on chromosome 15 (35,237,326 to 35,238,062, forward strand). Ensembl gene ENSG00000259516.
Diseases named in the same sentence as ANP32AP1 in open-access papers:
ANP32AP1 is named in the same sentence as 1 disease in open-access papers, as found by Europe PMC text mining. Sharing a sentence is not in itself a finding about the gene and the disease. The quoted sentences say what the papers report.
cancer (1 paper, 2021). A tumor composed of atypical neoplastic, often pleomorphic cells that invade other tissues. "HHIPL2, XPO1, SALRNA1, ZBTB45, ANP32AP1, ACTR3BP5, LOC100129138, GPR45, and CAB39L gene deletions were associated with non-cancer subjects without FCH (p < 0.05), while RAB9BP1, LOC101928523, and MALRD1 gene deletions were related to non-cancer patients with FCH (p < 0.05)." (PMID 33431054, 2021).